NANOG (Nanog homeobox)
Diseases named in the same sentence as NANOG in open-access papers (continued):
Sharing a sentence is not in itself a finding about the gene and the disease.
ovarian carcinoma (continued). "Further studies to elucidate the functional crosstalk between NANOG and AMPK pathways in ovarian cancer cells may result in the identification of therapeutic targets, paving the way for more effective and safe manner." (PMID 36114703, 2022). "As AMPK has been shown to be involved in modulating NANOG stability and expression, we also investigated whether AMPK regulates stemness‐related gene expression in ovarian cancer cells." (PMID 36114703, 2022). "We previously found that PGCCs could form spheroids in stem cell medium and acquired embryonic stemness marked by expression of OCT4, NANOG, and SOX2, which are involved in ovarian cancer relapse." (PMID 34588424, 2021). "NANOG controls cell migration and invasion by regulating FOXJ1 expression in ovarian cancer." (PMID 34109184, 2021). "Green fluorescent protein (GFP)-labeled ovarian CSCs utilize the NANOG promoter system to overexpress OCT4, SOX2, and NANOG compared with the GFP-negative ovarian cancer cells, and the GFP-positive cells also exhibit greater cisplatin resistance and tumor initiation properties." (PMID 34064635, 2021). "Moreover, DCs charged with total lysates of Panc-1 CSCs and loaded with Nanog homeobox (NANOG) peptide evoke strong anti-tumor responses in pancreatic and ovarian cancer, respectively." (PMID 34572009, 2021). "FOXP1 upregulates the transcriptional activities of four key stemness factors, ATP Binding Cassette Subfamily G Member2 (ABCG2), octamer-binding transcription factor 4 (OCT4), nanog homeobox (NANOG) and SOX2, to promote CSCs-like features in ovarian cancer cells." (PMID 33898430, 2021). "Clinical, in vitro and in vivo evidence strongly suggested that upregulation of HK2 in ovarian cancer was correlated with metastasis and poor survival and mediated migration, invasion and stemness via PTK2/MAPK1/3/MMP9/NANOG/SOX9 signaling cascades in vitro and in a nude mouse model." (PMID 33052246, 2020). "In addition, pluripotent stem cell markers of normal stem cells, notably OCT4, NANOG and SOX2, have also been found to play an important role in ovarian cancer development and metastasis and can be used to verify cell stemness." (PMID 32169072, 2020). "Besides NANOG and SOX9, we also revealed an up-regulation of OCT4, KLF4, and CD117 by HK2 in ovarian cancer, which further supports the concept that HK2 regulates CSCs." (PMID 31212816, 2019). "Based on previous studies relating to these mRNA, CA11 and MEDAG may be involved in maintaining malignant ascites microenvironment, while LAMA4, NANOG and SPINT2 activities could regulate ovarian cancer progression and metastasis." (PMID 29499737, 2018). "Expression of stem cell markers (OCT4, SOX2, NANOG, NESTIN, ABCG2, CD133 and CD117) in ovarian cancer (sphere cells) represent their tumorigenic potential, and resistance to cisplatin, paclitaxel, adriamycin and methotrexate, which highlights the significance of “stemness” of cancer cells." (PMID 30121075, 2018). "The aim of this study was to focus on in situ morphological changes in the ovarian surface epithelium of tumor tissue in women with epithelial ovarian cancer after we applied the antibodies for markers of EMT vimentin and pluripotency-related markers NANOG, SOX2 and SSEA-4." (PMID 28231820, 2017). "Besides NID1, several regulators, such as HPIP, NANOG and FOXM1, have been reported to promote EMT of ovarian cancer cells and then confer them drug resistance, involving PI3K/AKT pathway, STAT3 pathway, etc." (PMID 28416770, 2017). "Similarly, promotion of EMT by hematopoietic PBX interacting protein, NANOG, TWIST1, SNAI1 FOXM1 accompanied acquisition of ovarian cancer cell resistance to conventional therapeutic agents, such as cisplatin, carboplatin or paclitaxel." (PMID 28792442, 2017).
ovarian carcinoma (continued). "Though broader spectrum of CSCs may need to be tested to evaluate how common FOXP1 to core CSC transcription network, FOXP1 up-regulates expression of CSC-related core transcription factors, including ABCG2, OCT4, NANOG, and SOX2, in ovarian cancer cells." (PMID 26654944, 2016). "In addition to the effects on cell migration and invasion, we believe our identification of the downstream pathways of HK2—Namely the HK2 to FAK to MEK-1/ERK1/2 pathway that controls NANOG and SOX9 expression and ovarian cancer CSC properties—Will be of significant importance to future studies." (PMID 31212816, 2019). "Importantly, we detected HLA class I on NANOG positive cells in ascites of ovarian cancer patients, whereas NANOG negative tumor cells were partially HLA class I negative." (PMID 29971070, 2018). "However, to our knowledge, to date, no comprehensive study has characterized SOX2, OCT4, and NANOG in the most commonly used ovarian cancer cell lines or determined whether their expression correlates with specific surface markers and other features of TICs." (PMID 33445692, 2021). "NANOG-GFP was useful in characterizing CSCs of triple-negative breast cancer and ovarian cancer." (PMID 34150761, 2021). "Stem cell markers NANOG and ABCG2/BCRP1 were colocalised in both SP and non-SP cells, and the specific individual cells in ovarian cancer tissues, as illustrated in our study, make it reasonable to hypothesise that there are cancer stem-like cell niches in ovarian cancer." (PMID 20354527, 2010).
prostate carcinoma (52 papers, 2011 to 2025). A carcinoma that arises from epithelial cells of the prostate gland. "In prostate cancer, NANOG is highly associated with cancer stem cell traits and resistance to androgen deprivation therapy." (PMID 36969009, 2023). "In xenotransplantation assays, NANOG promoted tumorigenesis and sustained, in prostate cancer cells, the expression of stem-associated markers, such as CD133, ALDH1 and CXCR4." (PMID 31366128, 2019). "We have shown that prostate cancer (PCa)-associated NANOG is derived primarily from NANOGP8 and is enriched in CD44+ PCa stem/progenitor cells, and inversely correlates with differentiation factors androgen receptor (AR) and prostate-specific antigen (PSA)." (PMID 27867534, 2016). "Human cultured prostate cancer cells, prostate cancer xenografts and primary prostate cancer cells express a functional variant of NANOG, NANOG mRNA, in cancer cells." (PMID 25120646, 2014). "Moreover, extensive loss-of-function analyses revealed that RNAi-mediated NANOG knockdown inhibited xenograft tumor development in several prostate cancer cell lines." (PMID 29156833, 2017). "NANOG, a homeobox TF, is also a biomarker of tumor pluripotency in various cancers, such as ovarian, breast, and prostate cancers, with NANOG stability being assured through phosphorylation by ERK and cyclin-dependent kinase 1 (CDK1)." (PMID 39860065, 2025). "OCT4, in coordination with SOX2 and NANOG, acts as a master regulator of stemness and is frequently upregulated in prostate cancer stem cells (PCSCs)." (PMID 40722714, 2025). "NANOG silencing decreases phosphorylation events in TGF-β/SMAD signaling components which leads to the inhibition of prostate cancer stem cells proliferation, cell cycle arrest and induction of apoptosis." (PMID 36672280, 2023). "A study reported that AMPK promotes Speckle‐type POZ protein (SPOP)‐mediated NANOG ubiquitination and degradation in prostate cancer." (PMID 36114703, 2022). "We previously found that DU145 cells (human prostate cancer cell line) require the expression of NANOG, a stem cell-related transcription factor, to resist anticancer drugs and escape immune surveillance." (PMID 36564568, 2022). "It has been also suggested that NANOG associates with androgen receptor (AR) and FOXA1 to regulate pro‐differentiation genes and castration resistance in prostate cancer." (PMID 33439550, 2021). "In this study, we used flow cytometry to isolate CD44+/CD133+/NANOG+ PCSCs from DU145 prostate cancer cells." (PMID 33336042, 2020). "In another study, androgen receptor signaling was found to upregulate NANOG mRNA and protein, directly contributing towards prostate cancer." (PMID 32765953, 2020). "NANOG is a key factor in regulating the growth of PCSCs and is a possible target for the treatment of prostate cancer." (PMID 33336042, 2020). "Recent studies with patient samples and cell lines indicate that SPOP-mediated degradation of NANOG helps prevent prostate cancer progression." (PMID 31624231, 2019). "Co-immunoprecipitation experiments in SW1990 cells showed that SPOP interacted with the stem-cell marker NANOG, and this interaction has recently been shown to play a critical role in regulating progression of prostate cancer." (PMID 31624231, 2019). "Particularly, SPOP inhibits the self-renewal and stem cell properties of prostate cancer cells via the ubiquitinating-dependent degradation of NANOG regulated by AMPK activation or by direct interaction with NANOG." (PMID 31366128, 2019). "Reports in the literature have documented the association between LIN28, NANOG, POU5F1, and SOX2 and prostate cancer aggressiveness individually." (PMID 31146720, 2019). "NANOG expression in prostate cancer was particularly evident at the level of a progenitor/stem CD44+ tumor compartment." (PMID 31366128, 2019). "ONC201 significantly downregulated CSC-related genes ABCB5, ALDH1A1, ALDH7A1, WNT16, CD133 and NANOG in DU145 prostate cancer cells." (PMID 28767654, 2017).
prostate carcinoma (continued). "In the future it will be interesting to determine the correlation of CD44v6 and NANOG in the chemoresistant A3 prostate cancer cells and in the progression and invasion of prostate cancer." (PMID 29156833, 2017). "Here we first show that endogenous NANOG is required for the growth of castration-resistant prostate cancer xenografts." (PMID 27867534, 2016). "We previously reported that inducible NANOG expression propels the emergence of aggressive castration-resistant prostate cancer phenotypes." (PMID 27867534, 2016). "NANOG expression in prostate cancer is highly correlated with cancer stem cell characteristics and resistance to androgen deprivation." (PMID 26087476, 2015). "The immunohistochemical intensity of prostate cancer was weakest for NANOG followed by OCT4, with the strongest staining for CD133 and NESTIN." (PMID 25120646, 2014). "When specimens were diagnosed as prostate cancer, immunohistochemical analysis of the four different stem cell markers (NANOG, OCT4, CD133 and NESTIN) and hypoxia-inducible factor (HIF)-1α was performed." (PMID 25120646, 2014). "The CSC markers, in particular OCT4 and NANOG, were immunohistochemically expressed in prostate cancers." (PMID 25120646, 2014). "The expression score for NANOG in the prostate cancer cells was significantly greater than that of cells in high-grade PIN and the hyperplastic glands (P<0.001 for each comparison)." (PMID 25120646, 2014). "One notable observation in the current study was that prostate cancer cells expressing NANOG and OCT4 were also positive for HIF-1α reactivity." (PMID 25120646, 2014). "In prostate cancer, NANOG (P<0.001) immunoreactivity was the strongest among the four stem cell markers." (PMID 25120646, 2014). "Results showed that eNOS overexpression could induce remarkable upregulation of multiple CSCs markers (CD133) and stemness-associated genes, especially transcription factors NANOG and SOX2, in prostate cancer cells under adherent 2D culture." (PMID 35526071, 2022). "Finally, the orphan nuclear receptor NR2F1 has been linked to tumor cell dormancy in prostate cancer through induction of pluripotency genes, such as SOX2 and NANOG." (PMID 32220301, 2020). "Another small molecule inhibitor of PIN1, PiB, inhibited both SPOP-mediated NANOG degradation and stemness-associated spheroid formation in prostate cancer cells; the application of PIN1 inhibitors against prostate cancer with wild-type SPOP was suggested by the researchers." (PMID 32268506, 2020). "More recent studies have better defined the role of NANOG in the biology of prostate cancer." (PMID 31366128, 2019). "Therefore, NANOGP8 is likely a primary contributor of NANOG protein expression in various somatic cancers, including prostate cancer." (PMID 26087476, 2015). "The findings of the current study suggested that NANOG expression may be a biomarker for the diagnosis of prostate cancer, and the coexpression of NANOG and HIF-1α may be involved in prostate carcinogenesis." (PMID 25120646, 2014). "Pluripotency-associated transcription factors, including NANOG, Sox2 and OCT4, are known as regulators of cellular identity in ES cells and have recently been identified in the epithelial malignancies of a variety of tissues, including prostate cancer." (PMID 25120646, 2014). "Notably, NANOG was demonstrated to reprogramme prostate cancer cells by repressing the AR signalling axis and activating its own distinct transcriptional programme as well as engaging that of others such as MYC, leading to acquisition of a castration-resistant stem cell-like state." (PMID 30742096, 2019). "Therefore, NANOG is an emerging focus in developmental biology, due to its importance in the maintenance of self-renewal and multipotential capacity in a variety of malignancies, including prostate cancer." (PMID 25120646, 2014). "In addition, the immunohistochemical expression of NANOG may present as a biomarker for investigating the pathobiology of prostate cancer." (PMID 25120646, 2014).
prostate carcinoma (continued). "Some of these proteins including AR, SMAD, NANOG, EZH2, and KLF have demonstrated prognostic significance in advance-stage prostate cancer." (PMID 36672280, 2023). "In PC-3 prostate cancer cells, POLR3G is directly regulated by NANOG, and reciprocally influences the levels of NANOG through the expression of DR2 Alu elements." (PMID 36710885, 2022). "Overall, our findings demonstrated the significant, reproducible upregulation of a number of genes particularly the stem cell markers NANOG, OCT4/POU5F1 and ALDH1 in prostate cancer holoclones." (PMID 32647229, 2020). "RNAi-mediated NANOG knockdown leads to attenuated cancer stem cell (CSC) properties such as sphere formation and clonogenic efficiency in breast and prostate cancer cells." (PMID 32820157, 2020). "NANOG and OCT4 are expressed in primary prostate cancers, where their expression positively correlated with increased prostate tumor Gleason score." (PMID 31366128, 2019). "Among the isolated populations from primary prostate cancers, only CD44+ CD133+ cells display in vitro self-renewal and express core stem cell genes OCT4, NANOG, SOX2, nestin, and c-kit." (PMID 31878027, 2019). "Previous studies also found that the embryonic markers SOX2, NANOG, and OCT4 were elevated in CSCs isolated from human prostate cancer tissue, human prostate tumor models, and some prostate cancer cell lines." (PMID 30558236, 2018). "(OCT4, 19%; SOX2, 29%; NANOG, 14%; LIN28A, 9%; KLF4, 29%); the SOX2 and KLF4 genes were amplified predominantly in prostate cancer." (PMID 30287838, 2018). "Prostate cancer cells with an EMT phenotype induced by PDGFD displayed CSC features, including increased expression of SOX2, NANOG, OCT4, and Notch-1, and enhanced sphere-forming ability and rapid tumor growth in vivo." (PMID 30227608, 2018). "Both NANOG and CD44 expression levels have been shown to correlate in human PC3 prostate cancer cells." (PMID 29156833, 2017). "Prostate cancer derived-CSCs that were treated with decitabine showed decreased expression of stemness genes Octamer-binding transcription factor 4 (OCT40029 and Nanog homeobox (NANOG), leading to overall reduction in tumor growth." (PMID 28148257, 2017). "Expression of NANOG, particularly in conjunction with HIF-1α, was proposed as a biomarker for prostate cancer." (PMID 27764770, 2016). "We established NANOG- and NANOGP8-knockout DU145 prostate cancer cell lines using the CRISPR/Cas9 system." (PMID 26087476, 2015). "The results of this study showed that of the four CSC markers examined (NANOG, OCT4, CD133 and NESTIN), NANOG was intensively expressed in prostate cancer." (PMID 25120646, 2014). "High-grade prostate intraepithelial neoplasia (PIN) was positive for NANOG and OCT4; however, the number of positive cells was fewer than that of prostate cancer." (PMID 25120646, 2014). "The expression of NANOG, OCT4, CD133 and NESTIN in prostate ADCs with high Gleason scores (>3+4) was greater than that in prostate cancers with low Gleason scores (<3+3), although this difference was not significant." (PMID 25120646, 2014). "Our analysis of 22Rv1 stem/progenitor cell marker gene expression revealed a small increase in NANOG and reduction in SOX2 in GSK-3α-silenced cells, inconsistent with selection for prostate cancer stem/progenitor-like cells." (PMID 25327559, 2014). "With regard to prostate cancer, several studies have recently suggested the positive reaction of adenocarcinoma (ADC) cells against NANOG." (PMID 25120646, 2014). "NANOG and OCT4 were also found to be expressed in highly invasive cell populations from other tumors such as prostate cancer and glioma." (PMID 21526207, 2011).